FOXO3 (forkhead box O3)
Diseases named in the same sentence as FOXO3 in open-access papers (continued):
Sharing a sentence is not in itself a finding about the gene and the disease.
tumor (continued). "The atrophic effect of the tumor was also illustrated by a large increase in the expression of the Atrogin-1 and MurF1 atrogenes, and a significant increase in the expression of the Foxo1 and Foxo3 transcription factors, which are positive regulators of atrogene expression." (PMID 22257771, 2012). "Key predictors included clinical variables (age, tumor size, NPI, radiotherapy) and molecular markers (ATM, HERC2, AKT2, FOXO3, CYP3A43)." (PMID 41300329, 2025). "Feature selection was performed using the Boruta algorithm, which revealed that both clinical parameters (e.g., age, tumor size, NPI, radiotherapy) and transcriptomic biomarkers (e.g., ATM, HERC2, AKT2, CYP3A43, FOXO3) provided strong prognostic contributions." (PMID 41300329, 2025). "Although our study has some limitations, the available data still support that SHMT1 inhibits tumor cell proliferation, invasion and EMT and increases the level of apoptosis by inhibiting AKT/FOXO3 A signaling pathway." (PMID 40442541, 2025). "We found that FOXA1 and FOXM1 were significantly positively correlated with tumor purity in patients with BRCA, while FOXC2, FOXO3, FOXP1, and FOXQ1 were significantly negatively correlated with tumor purity in patients with BRCA." (PMID 38608123, 2024). "The immunohistochemical data of FOXO3, sourced from the HPA database, showcased higher fluorescence intensity in normal tissues compared to tumor tissues." (PMID 37976368, 2024). "To further explore the mechanism by which SIRT1 induces hormone resistance, we examined the expression of SIRT1, FOXO3, LC3B, and p62 proteins in EC tumor tissues from mice using immunohistochemistry." (PMID 39266959, 2024). "Gene expression studies indicated that cell death in response to microgravity was due to the upregulation of the tumour suppressors PTEN and FOXO3." (PMID 38693857, 2024). "As a basic member of Forkhead Box O (FOXO) family, FOXO3 regulated the proliferation of B lymphocytes and played role in patients with DLBCL by inhibiting tumour growth." (PMID 37987202, 2024). "Studies have found that FOXA1, FOXM1, FOXO3, FOXP1, and so on play an important role in tumors as oncogenes or tumor suppressor genes." (PMID 38608123, 2024). "Silencing FoxO3 in Foxp3GFP−creRorcfl/fl mice accelerates tumor development, accompanied by increased IL-6 and STAT3 expression within the tumor tissue." (PMID 38317142, 2024). "The expression of ANAPC11 was detected in tumor sections by IHC staining, and knockout of ANAPC11 was found to induce increased expression of FOXO3, p21, and GULP1 and decreased expression of Ki67, a well-known marker for cell proliferation." (PMID 37573356, 2023). "RELB, NFKB1, BCL3, and FOXO3, found in NEAT1+ tumor cells, were closely related to the CSCs phenotype." (PMID 37430270, 2023). "The tumour suppressive substrates include inhibitor of nuclear factor kappa B (IκB), programmed cell death protein 4 (PDCD4) and forkhead box protein O3 (FOXO3)." (PMID 37293994, 2023). "Six key genes were located within malignant tumor cells and enriched predominantly in the cytoplasm of tumor cells, including PERP, BAK1, VDAC1, FOXO3, AKT3, and IGF1." (PMID 36900213, 2023). "Translocations in FOXO3/PDGFD and DDX10/SKA3 are interesting due to their possible role in tumor cell growth and survival." (PMID 36831263, 2023).
tumor (continued). "The "O" subfamily of forkhead box transcription factors consists of four members, including FOXO1 (FKHR), FOXO3 (FKHRL1), FOXO4 (AFX), and FOXO6, generally considered tumor suppressors via inducing apoptosis and inhibiting proliferation." (PMID 37821870, 2023). "On the other hand, there are also plenty of reports of TFs acting as tumor suppressors in CRC; among them is FOXO3, whose downregulation correlates with a better prognosis in CRC patients." (PMID 38132443, 2023). "As tumor suppressors, FOXO1 and FOXO3 were suggested to be downstream mediators of CRC cancer health disparities." (PMID 37081981, 2023). "Interestingly, others showed that K271 on FOXO3 was methylated by SETD7, which decreases FOXO3 protein stability while moderately enhancing FOXO3-dependent activation of pro-apoptotic genes, which may in turn affect FOXO3’s ability to promote tumor suppression." (PMID 35812730, 2022). "The FOXO3/FOXM1 axis is an essential downstream signal of the PI3K/AKT, Ras/ERK, and JNK/p38MAPK pathways, which are also involved in the tumor growth mediated by controlling the cell cycle." (PMID 36619388, 2022). "In gastric cancer, circ-Foxo3 upregulates the expression of USP44 by targeting miR-143-3p, thereby exerting a tumor-promoting effect." (PMID 36139427, 2022). "Other 6q15 genes with potential tumor suppressive functions for example include EEF1A1, ZNF292, SNORD50A, PRDM1, CCNC, FOXO3, WISP3, and FRK." (PMID 34625909, 2022). "FOXO3, a transcription factor that can inhibit the transcription of SOX2, has tumor-suppressive functions in CSCs." (PMID 34795388, 2022). "Our findings demonstrated that the tumour growth had improved in response to LINC00472 silencing, while the tumour growth was inhibited after FOXO3 overexpression." (PMID 34363438, 2021). "Articles analyzing FOXO3 levels in HCC patient samples and its relationship with tumor development, survival or clinicopathological factors were selected." (PMID 34771514, 2021). "Later, FOXO3 leads to the upregulation of its downstream effector proteins including pro-apoptotic proteins, such as PUMA and BAX leading to the apoptosis of tumor cells." (PMID 35087404, 2021). "MiR-551b functions through the suppression of forkhead box O3 (FOXO3) and tripartite motif containing 31 (TRIM31), two important tumor suppressors." (PMID 34512721, 2021). "FOXO3 is a well-established tumor suppressor gene involved in various cellular processes; GRHL3 is necessary for differentiation and has a tumor-suppressing role." (PMID 34163012, 2021). "FOXO3 has been identified as a potent repressor of EMT-related transcription factors such as Snail, which has led to a better understanding of its tumor suppressive function." (PMID 35008549, 2021). "Using TMAs constructed from human GBM formalin-fixed paraffin-embedded tumor samples (n = 89), we used semiquantitative immunohistochemistry to analyze the level of protein expression of SOX2 and FOXO3." (PMID 36303712, 2021). "One of these, FOXO3 (also referred to as FOXO3a, or FKHRL1 in the older literature) is of considerable interest in many therapeutically relevant areas, such as tumor therapy and longevity research." (PMID 34201262, 2021).
tumor (continued). "On the one hand, the widely studied FOXO1 regulates cellular function as a tumor inhibitor; on the other hand, FOXO3 and FOXO6 play important roles in promoting tumor growth and invasion and maintaining tumor survival." (PMID 34123834, 2021). "In GC, sEV-resident miR-155 was show to target Forkhead box O3 (FOXO3a) as well as c-MYB, thus enhancing the expression of VEGF in vascular cells to induce angiogenesis and tumor growth." (PMID 34503190, 2021). "As a member of the Forkhead box class O transcription factor family, highly expressed FOXO3 in HCC executes tumor-promoting activities during oncogenesis and progression, and it is involved in various tumor processes." (PMID 37304672, 2021). "Inactivation of tumor suppression function of FoxO3 is related to human development of BTC and metformin activates the AMPK-FoxO3 pathway resulting in a reduction of intracellular reactive oxygen species." (PMID 33194743, 2020). "On the contrary, as a tumor promoter, FOXO1 and FOXO3 work in tandem in negatively regulating cytotoxicity of CD8+ T and NK cells against tumor cells." (PMID 33396222, 2020). "Generally, miR-182-5p regulates the apoptosis of tumor cells by targeting certain special genes, such as FOXO1, MTSS1, HMGA2, CASP9, and FOXO3, and these target genes were also predicted by our experiment." (PMID 32090086, 2020). "For example, circ-Foxo3 prevents mouse double-minute 2 (MDM2) from inducing Foxo3 ubiquitination and degradation, resulting in increased levels of Foxo3 protein and tumor cell apoptosis." (PMID 32460831, 2020). "Consistent with the in vitro findings, suppressing both AMPK and FOXO3 in SIRT1-overexpressing xenograft tumors substantially reversed the improved cisplatin sensitivity, as indicated by the tumor volumes and TUNEL staining." (PMID 32051395, 2020). "Inhibition of FOXO3 expression promotes EOC cell proliferation and tumor progression, suggesting that FOXO3 exerts anti-tumor effects." (PMID 31013711, 2019). "The members of the FOXO subclass (FOXO1, FOXO3, FOXO4 and FOXO6) are involved in a wide range of key biological processes including apoptosis, cell cycle, stress resistance, tumor resistance, differentiation, and metabolism." (PMID 31450545, 2019). "In a murine bladder tumor model, the combination of FOXO3 shRNA and the Her2/neu DNA vaccine significantly enhanced CD8+ T cell-dependent cytotoxic activity and the anti-tumor effect in a murine tumor model." (PMID 30658461, 2019). "PTEN is a well-established tumor suppressor and increasing studies have suggested it inhibits tumor growth through upregulating FOXO family members such as FOXO3 and FOXO4." (PMID 30064475, 2018). "The results delineate increased expression of angiogenic and oncogenic markers CXCR4, SDF-1, and decreased expression of tumor suppressor genes, IRF1, LDOC1, and FOXO3 in CP patient tissues." (PMID 30413788, 2018). "Consistent with an in vitro study, our immunofluorescence analysis on the tumour sections of EGCG and PDE3 inhibitor-injected mice demonstrated that the combination regimen also suppressed both FOXO3 and CD44 expression." (PMID 28507327, 2017). "To shed light on the in vivo molecular mechanisms underlying the AMPK/FoxO3 interplay, we analyzed AMPK(Thr172) and FoxO3(Ser413) phosphorylation levels in TA muscles from vehicle, (−)-JQ1 and (+)-JQ1 tumor-bearing mice." (PMID 29167426, 2017). "The FOXO family members, FOXO1, FOXO3 and FOXO4, are ubiquitously expressed transcription factors that function as tumor suppressors through inhibiting the expression of genes promoting proliferation, survival or de-differentiation." (PMID 27966458, 2017).
tumor (continued). "FOXO3, like FOXM1, is a forkhead transcription factor, a typical tumor suppressor and a functional antagonist of the oncogene FOXM1." (PMID 28482906, 2017). "AMPK was strongly activated in muscles of C26 vehicle and (−)-JQ1-treated tumor-bearing mice; the increase in AMPK(Thr172) phosphorylation paralleled a concurrent dramatic increase in FoxO3(Ser413) phosphorylation." (PMID 29167426, 2017). "We therefore investigated FoxO3 recruitment to MAFbx/Atrogin1, MuRF1, and GABARAPL1 promoters in skeletal muscles from control and (−)-JQ1 and (+)-JQ1-treated C26-tumor-bearing mice by ChIP qPCR." (PMID 29167426, 2017). "The circ-Foxo3-p21-CDK2 ternary complex can suppress cell cycle progression and inhibit tumor growth." (PMID 29349062, 2017). "Together, these findings suggested the potential interplay between the tumor suppressors IGFBP1 and FOXO3, and the feedback regulatory axis, resulting in reciprocal pathways that mediated the overall response of UA in HCC cells." (PMID 27036874, 2016). "The RT-PCR results suggested that FOXO3 was highly downregulated in tumor cells, yet CTNNB1 was remarkable upregulated in tumor cell." (PMID 26915315, 2016). "In contrast to normoxia, where FOXO3-activation reduced growth of both cell types, hypoxic conditions inverted the FOXO3-response in STA-NB15 cells leading to an increased number of viable, metabolically-active tumor cells." (PMID 27769056, 2016). "This recurrent abnormality, which is observed in 29-52% of ENKTCL arising in immunocompetent individuals, encompasses loci of the FOXO3 and PRDM1 genes, which have been shown to function as tumor suppressors in ENKTCL and subtypes of PTCL." (PMID 27203213, 2016). "As the majority of tumours arising in the MYC10 mice are Mac1+Gr1−, it is likely that the increase in this population in FoxO3−/−MYC10 mice is a factor in the acceleration of tumour onset." (PMID 26764572, 2016). "Further analysis suggested that miR-551b functioned through the suppression of Foxo3 and TRIM31, two important tumor suppressors." (PMID 27743201, 2016). "It was shown that miR-155 targets several tumor suppressors such as SOCS1, FOXO3, and VHL and is involved in the regulation of cell survival, growth, chemosensitivity and tumor angiogenesis." (PMID 26156018, 2015). "Skeletal muscle expresses three FoxO family members, including FoxO1, FoxO3 and FoxO4, with both FoxO1 and FoxO3a significantly upregulated in cachectic muscles from LLC and C26 tumor-bearing mice." (PMID 25539728, 2014). "Other targets of up regulated miRNAs in different treatment conditions also includes proteins that inhibit tumor progression, such as DNMT3A, FADD, pTEN, FOXO3, DDX20 and PA2G4 (EBP1)." (PMID 24387052, 2014). "In accordance with the expression levels of miR-182, there were reduced expressions of FOXO3 and FOXO1 in tumor vs. normal tissues in the SBU cohort." (PMID 24865442, 2014). "Under hypoxic conditions, FOXO3 prevents hypoxia-induced ROS and HIF-1α stabilization by ROS, which contributes to tumor growth in xenograft models." (PMID 23801966, 2013). "Another study revealed the essential function of FoxO3 in inhibiting differentiation of AML cells, which varies from its classic function as a tumor suppressor." (PMID 24376685, 2013). "So FOXO3 is a transcription factor that directly or indirectly affects mitochondrial respiration, ROS accumulation and even mitochondrial shape, which on one hand affects apoptosis sensitivity of tumor cells, but also may have significant impact on life-span in multicellular organisms." (PMID 23801966, 2013). "Phosphorylation of FoxO3 via the AKT, IKK, and ERK pathways leads to deregulation, cytoplasmic retention, degradation of FoxO3 and favors tumor progression." (PMID 22489133, 2012).
tumor (continued). "Increased accumulation of LDs in tumor cells involves several signaling pathways, such as activation of the epidermal growth factor receptor and PI3K/AKT/ mammalian target of the rapamycin (mTOR) pathways and inactivation of the FOXO3/SIRT6 pathway." (PMID 38500157, 2024). "Additionally, the expression levels of FOXP3, FOXO3, FOXO1, FOXA2, and FOXM1 were found to be elevated in GBM tissues from the TCGA database compared to non-tumor brain tissues, while the level of FOXQ1 was reduced." (PMID 38561331, 2024). "This can be attributed to the low expression of CTLA-4 by IL-17-producing Tregs, which leads to Forkhead box O 3 (FoxO3) inactivation in DCs and the activation of the IL-6 production-STAT3 signaling pathway in tumor cells, ultimately promoting their proliferation." (PMID 38317142, 2024). "Moreover, the Forkhead box class O (FoxO) family of transcription factors is composed of FoxO1/FKHR, FoxO3/FKHRL1, FoxO4/AFX, and FoxO6, which regulate cellular homeostasis, autophagy, angiogenesis, tumour growth, and metastasis." (PMID 37174088, 2023). "To better understand factors that may account for the contrasting tumour suppressor status of FOXO3 and FOXO1 in ALL, we compared RNA-sequencing data from 697 cells transduced with SIN-SIEW-FOXO1, SIN-SIEW-FOXO3 or empty vector." (PMID 36670235, 2023). "Notably, RT was able to prevent the elevation of some important proteolytic transcriptional factors (p-STAT3, FoXO1, FoXO3) and key proteins in UPS and autophagy pathways, conferring protection against muscle wasting in tumor-bearing mice." (PMID 35847939, 2022). "Moreover, we demonstrated ectopic expression of IFITM3 suppressed FOXO3 expression, consequently led to c-MYC induction to promote tumor growth, cell metastasis, cancer stemness as well as chemoresistance." (PMID 35941699, 2022). "Even though various studies have been done to acknowledge the tumour-suppressive or oncogenic role of FOXO3 in cancer, still there exist a lack of understanding in terms of cancer prognosis and treatment." (PMID 36727057, 2022). "Furthermore, we report on the elevation of tumor-specific transcription factors such as RUNX1 and GABPB1, and the reduced expression of FOXO3 that is low in the advanced group." (PMID 35626705, 2022). "For example, circ-Foxo3 can form a Foxo3-p21-CDK2 ternary complex by interacting with cyclin-dependent kinase 2 (CDK2) and p21, resulting in the inhibition of CDK2 function and the blockage of cell cycle progression, thereby regulating tumor development." (PMID 36465346, 2022). "The extent to which FOXO3’s pro-longevity functions overlap with its tumor-suppressive mechanisms is not known." (PMID 36303712, 2021). "Similarly to FOXO3/4, FOXN3 overexpression decreases β-catenin/TCF7L2 interaction in CRC cell lines, and depletion of FOXN3 increased tumor growth and metastasis in mice." (PMID 34298659, 2021). "Furthermore, qRT-PCR analysis revealed that SLC2A3, FOXO3, EGFR and GPC1 were upregulated in tumor samples." (PMID 33962639, 2021). "Furthermore, subcutaneous injection of circ-Foxo3-, Foxo3-, Foxo3P-transfected MDA-MB-231 cells into nude mice indicated that tumor growth in mice receiving transfected cells was notably slower than those received the control cells." (PMID 34400888, 2021). "MMP, OXSR-1, TAC, FOXO-3 and MMP-9 were measured in tumour cell lysates by the ELISA technique." (PMID 34072756, 2021). "Taken together, depletion of TAM-derived exosomal miR-29a-3p could lead to downregulation of PD-L1 expression via the FOXO3-AKT/GSK3β axis, thereby inhibiting tumor formation and immune escape in vivo." (PMID 34589270, 2021). "Therefore, when considering the oncogenic role of JAK2 and tumor-suppressive role of FOXO3, nuclear localization of IL4Rα/IL13Rα1 exerts its role by involving JAK2-FOXO3 interaction in the progression of STSs." (PMID 33419470, 2021).